SCAF11 (SR-related CTD associated factor 11)
Description:
Plays a role in pre-mRNA alternative splicing by regulating spliceosome assembly.
Synonyms: SRrp129; CASP11; SFRS2IP; SIP1; SRSF2IP
Tractability: PROTAC: UniProt records ubiquitination sites on it; ubiquitination databases record sites on it; its protein half-life has been measured.
Gene: Protein-coding gene on chromosome 12 (45,919,131 to 45,992,120, reverse strand). Ensembl gene ENSG00000139218.
Subcellular location: Nucleus
Subcellular location (Human Protein Atlas): Nucleoplasm; Nuclear bodies; Nucleoli
Gene Ontology:
Molecular function: protein binding; RNA binding
Biological process: RNA splicing; RNA splicing, via transesterification reactions; spliceosomal complex assembly; mRNA processing
Cellular component: nuclear body; nucleolus; nucleoplasm; nucleus
Genetic constraint (gnomAD): Loss-of-function variants: 34 observed, 109.76 expected, observed/expected ratio (o/e) 0.31, 90% interval 0.23 to 0.41. The upper end of that interval is the gene's LOEUF score, 0.41, which puts it in group 1 of 6, group 1 being the genes least tolerant of losing a copy. Missense variants: 1,371 observed, 1,515.5 expected, observed/expected ratio (o/e) 0.9, 90% interval 0.86 to 0.95. Synonymous variants: 480 observed, 529.05 expected, observed/expected ratio (o/e) 0.91, 90% interval 0.84 to 0.98.
Homologues: Orthologues: chimpanzee SCAF11 (99% identical), macaque SCAF11 (94% identical), dog SCAF11 (82% identical), pig SCAF11 (79% identical), guinea pig SCAF11 (77% identical), rabbit SCAF11 (72% identical), rat Scaf11 (69% identical), mouse Scaf11 (68% identical), tropical clawed frog scaf11 (37% identical), zebrafish scaf11 (23% identical), Drosophila melanogaster CG2926 (13% identical). Paralogues in human: PHRF1 (18% identical), SCAF1 (12% identical).
Diseases named in the same sentence as SCAF11 in open-access papers:
SCAF11 is named in the same sentence as 68 diseases in open-access papers, as found by Europe PMC text mining. Sharing a sentence is not in itself a finding about the gene and the disease. The quoted sentences say what the papers report.
glioma (8 papers, 2021 to 2024). A benign or malignant brain and spinal cord tumor that arises from glial cells (astrocytes, oligodendrocytes, ependymal cells). "Additionally, Rop is available to stimulate oxidative stress and cell apoptosis of gliomas and repress cancer cell proliferation via controlling the circular RNA (circ) SCAF11/miR-145-5p axis." (PMID 35191804, 2022). "In glioma, ropivacaine could promote cell apoptosis and inhibit tumor growth, proliferation, migration, and invasion through the regulation of the circ-SCAF11/miR-145-5p axis." (PMID 36077665, 2022). "Interestingly, some upregulated genes found in RNA processing (MAGOH, SCAF11 and PLRG1) have been shown to play a role in tumorigenesis and cancer aggressiveness in glioma, liver, and gastric cancers." (PMID 36010871, 2022).
breast carcinoma (6 papers, 2021 to 2023). "The AQP3/SCAF11/FOXO1 axis was identified as the mechanism by which CAP targets breast cancer stemness." (PMID 38136293, 2023). "SCAF11 was identified to be PRG and used to construct prognostic risk prediction models in breast cancer." (PMID 36127654, 2022). "Furthermore, CASP8 (2%), NLRC4 (1%), NLRP3 (1%), NLRP2 (1%), PLCG1 (1%), NLRP1 (1%), NLRP7 (1%), SCAF11 (1%), GSDMC (1%), and NOD1 (1%) occurred somatic mutations as well as most of them had high frequencies of CNV in breast cancer." (PMID 34589498, 2021). "Decreased AQP3-19Y phosphorylation impaired SCAF11-mediated AQP3-5K K48-ubiquitination, resulting in compromised FOXO1 activity in breast cancer stem cell maintenance." (PMID 38136293, 2023).
liver cancer (2 papers, 2022 to 2023). An epithelial or non-epithelial malignant neoplasm that arises from the liver. "Suppression of SCAF11 expression inhibited the proliferation, attenuated the migration and invasion, and induced apoptosis of liver cancer cell lines." (PMID 35309514, 2022). "This study has demonstrated for the first time that SCAF11 promotes the progression of liver cancer." (PMID 35309514, 2022). "We found that the expression of SCAF11 was roughly upregulated in liver cancer tissue." (PMID 35309514, 2022). "In addition, our experiments confirmed that SCAF11 acted as an oncogene that might promote progression of liver cancer." (PMID 35309514, 2022). "The expression of CHMP4A, SCAF11, and GSDMC was high in liver cancer tissue." (PMID 35309514, 2022).
Autoimmunity (1 paper, 2016). The occurrence of an immune reaction against the organism's own cells or tissues. "SCAF11 is known to be involved in Behcet ́s disease that has some features of autoimmunity." (PMID 27257970, 2016).
bladder cancer (1 paper, 2022). "We found that 53.71% of all bladder cancer samples showed genetic mutations in the TCGA bladder cancer cohort and SCAF11 was the most frequent mutation frequency gene, followed by CASP8 and NLRP7." (PMID 36120583, 2022).
breast tumor (1 paper, 2022). "In vitro experiments indicated that SCAF11 was highly expressed in breast tumor cell lines." (PMID 35646948, 2022).
myocarditis (1 paper, 2025). Myocarditis is a condition that is characterized by inflammation of the heart muscle (myocardium). "Three SNPs (rs536572545, rs146289966 and rs142297026) near the SCAF11 gene were linked to pericarditis, while rs570375365 in the LRRC4C gene was associated with myocarditis." (PMID 40341528, 2025).
parasitic diseases (1 paper, 2022). "A peculiar subset of downregulated CD4+ and CD8+ cells expressed caspase-11 (Scaf11; cluster 10), indicating associated pyroptosis and cell death, potentially by gasdermin-dependent regulation of these cells at an early stage of infection, as found in other parasitic diseases." (PMID 35862712, 2022).
pericarditis (1 paper, 2025). An inflammatory process affecting the pericardium. "Next, considering all pericarditis (including perimyocarditis) cases (n = 31), significant associations were observed for the same three SNPs within or close to the SCAF11 gene: rs536572545, rs146289966, rs142297026." (PMID 40341528, 2025). "This suggests that SCAF11 is a target for further studies aiming to elucidate the pathogenesis of pericarditis attributed to COVID-19 vaccination." (PMID 40341528, 2025).
periodontitis (1 paper, 2022). An acute or chronic inflammatory process that affects the tissues that surround and support the teeth. "SCAF11 is involved in mRNA splicing and recently recognized as implicated in several types of cancer, but its involvement in periodontitis remains to be clarified." (PMID 35844512, 2022). "Among the PRG pairs, HMGB1 and SCAF11 showed the strongest positive correlation in periodontitis." (PMID 35844512, 2022).
tumor (21 papers, 2016 to 2025). "We further analyzed the association between SCAF11 expression level and tumor-infiltrating immune cells in BRCA with Xiantao Tool." (PMID 35646948, 2022). "Multiple tumor‐related pyroptosis signatures have also reported that high NOD2 and SCAF11 expression are associated with poor prognosis, but unfortunately, their mechanism in tumors has not been uncovered." (PMID 35651286, 2023). "Given the high expression of SCAF11 in BRCA tumor tissues, we knocked down SCAF11 expression with siRNAs in two BRCA cell lines, BT549 and T47D, and SCAF11 knockdown efficacy was verified by immunoblotting." (PMID 35646948, 2022). "There were apparently positive correlations between SCAF11 expression level and several tumor-infiltrating lymphocytes (TILs), including T central memory cell (Tcm), and type 2 T helper cell (Th2)." (PMID 35646948, 2022). "CPTP was found to be involved in pyroptosis, and while its pro-tumor function in DLBCL was discovered in our study, HTRA1, RBBP7, NFE2L2 and SCAF11 were found to be tumor suppressive." (PMID 36551263, 2022).
cancer (13 papers, 2005 to 2023). A tumor composed of atypical neoplastic, often pleomorphic cells that invade other tissues. "SCAF11 is expressed in many tissues, and diseases associated with SCAF11 include Corneal Endothelial Dystrophy as well as various types of cancer." (PMID 38152138, 2023). "SCAF11, also known as caspase-11, is a pro-inflammatory enzyme, which may have a role in cancer-associated angiogenesis." (PMID 36823654, 2023). "Knocking down SCAF11 possessed an anti-cancer effect in terms of inhibiting cell viability and suppressing colony-formation in in-vitro functional assays." (PMID 35646948, 2022). "The expression level of SCAF11 was up-regulated in BRCA, and knockdown of SCAF11 expression possessed an anti-cancer effect in inhibiting cell viability and suppressing of colony-formation." (PMID 35646948, 2022). "This work, for the first time, attributed the anti-cancer efficacy of CAP to its selectivity against cancer stemness, and proposed the AQP3/SCAF11/FOXO1 axis in mediating this process." (PMID 35637961, 2022). "We report AQP3-5K K48-ubiquitination via SCAF11 with AQP3-19F phosphorylation being essential, and demonstrate synergies between CAP and Atorvastatin towards enhanced anti-cancer efficacy." (PMID 35637961, 2022). "CTSG, NLRP9, DFNB59, APIP, SCAF11, CASP5 and NAIP showed significant downregulation across cancers." (PMID 36605187, 2022).
SCAF11 also shares sentences with these, for which no sentence is quoted: infection (30 papers); Sepsis (11); bacterial infection (5); colitis (5); endotoxemia (5); Salmonella Infections (4); melanoma (3); shigellosis (3); gram-negative bacterial infections (2); kidney disease (2); Obesity (2); steatosis (2); –CoV-2 infection (2); adenoma (1); alcoholic hepatitis (1); astrocytoma (1); Behcet ́s disease (1); Cirrhosis (1); CNS tumors (1); cognitive decline (1); Cognitive impairment (1); colon tumour (1); colorectal (1); colorectal cancer (1); coronary artery disease (1); cyst (1); cystitis (1); dementia (1); endothelial dysfunction (1); experimental autoimmune encephalomyelitis (1).
A further 26 diseases each share a sentence with SCAF11 in 1 paper.